STAT3 (signal transducer and activator of transcription 3)
Diseases named in the same sentence as STAT3 in open-access papers (continued):
Sharing a sentence is not in itself a finding about the gene and the disease.
liver diseases (continued). "STAT3 activation was observed in mouse models of liver injury and in human liver diseases in the context of inflammation and cancer." (PMID 24594856, 2014). "The total STAT3 was detected as an immuno-reactive 86 kDa band in all hepatic diseases, with slightly lower expression in CH, LDH, and CIRR." (PMID 17672890, 2007). "LIG not only suppresses HCC malignancy but also blocks tumor-associated macrophage recruitment and M2 polarization by inhibiting YAP/IL-6-driven activation of IL-6R/STAT3 signaling 5, suggesting therapeutic utility even in advanced, transformation-prone liver diseases." (PMID 40860128, 2025). "Gp130/STAT3 signaling is crucial for the pathogenesis of several liver diseases." (PMID 37391912, 2023). "In addition to the AMPK pathway, the STAT3 pathway is also critically involved in lipid metabolism and plays a pivotal role in the pathogenesis of liver diseases." (PMID 37630819, 2023). "Interestingly, while the role of STAT3 signaling was described in several liver diseases, the impact of direct STAT3 down-regulation in primary hepatocytes is still undefined so far." (PMID 36361830, 2022). "Furthermore, HCV infection has been shown to play an important role in development of liver disease via the IL-6/STAT3 pathway." (PMID 32266003, 2020). "However, in the context of a persistent inflammatory response, as observed during HCV infection, this sustained STAT3 activation favors liver disease development." (PMID 32357520, 2020). "This study indicates that STAT3 rs1053004 and rs1053005 polymorphisms and haplotypes formed by rs1053004 and rs1053005 are associated with chronic HBV infection and the haplotypes appear to be also associated with the development of liver disease." (PMID 29609539, 2018). "STAT3 rs1053004 and rs1053005 polymorphisms and haplotypes formed by rs1053004 and rs1053005 are associated with chronic HBV infection and the haplotypes appear to be also associated with the development of liver disease." (PMID 29609539, 2018). "It is, therefore, reasonable to hypothesize that polymorphisms in STAT3 may have predisposing effects on the susceptibility to HBV infection and HBV-related liver diseases." (PMID 29609539, 2018). "Moreover, mitochondrially associated HBx also leads to activation of transcription factors STAT-3 and NF-κB and mitochondrial translocation of Raf-1 via oxidative stress, which is relevant to liver disease pathogenesis." (PMID 26950437, 2016). "An interesting question arose in our study was whether dysregulation of glucose metabolism, lipid accumulation, inflammation, and fibrosis caused by STAT3 activation were limited to the MASH stage, since STAT3 plays different roles in different liver diseases or stages." (PMID 40066227, 2025). "Furthermore, STAT3 plays a key role in liver disease pathogenesis." (PMID 36615880, 2023). "In conclusion, our finding suggested that salidroside could ameliorate hypoxia‐induced liver oxidative stress and inflammation via Nrf2 and JAK2/STAT3 signaling pathways, which is likely to be a therapeutic candidate for the prevention and treatment of liver disorders at high altitudes." (PMID 34532015, 2021). "These overall procedures of STAT3 activation are responsible for ECM deposition, migration, and apoptosis in HSC and diverse liver disease." (PMID 31861943, 2019). "This study highlights the connection between STAT3/COX-2 signalling and gut microbiota alterations, providing a comprehensive therapeutic approach that could significantly influence the management of liver diseases." (PMID 41426367, 2025). "The role of STAT proteins in mediating liver inflammation and fibrosis has been well documented; however, approved therapies targeting STAT3 inhibition against liver disease are lacking." (PMID 38338338, 2024).
liver diseases (continued). "Therefore, more SNPs in STAT3 need to be genotyped in chronic HBV infection and HBV-related liver disease including HCC to clarify the detailed profile of STAT3 polymorphisms in HBV infection in future studies." (PMID 29609539, 2018). "Although STAT3 signaling might be more important than STAT5 in HCC progression and miR-196b could activate STAT3 by targeting SOCS2 in macrophages, previous work showed that importance of JAK2/STAT5 signaling in liver metabolism, liver diseases, and HCC36." (PMID 30988277, 2019). "However, no therapies targeting STAT3 inhibition against liver disease have been approved to date." (PMID 38338338, 2024). "This confirmed a mechanism: IL-6 major through p-STAT3 rather than p-STAT1 pathway affecting severity of inflammation and carcinogenesis in liver disease, particularly in HCC patients." (PMID 25908103, 2015).
injury (45 papers, 2012 to 2025). Damage inflicted on the body as the direct or indirect result of an external force, with or without disruption of structural continuity. "Targeting STAT3 signaling—either through activation or inhibition—represents a promising strategy for modulating OS and apoptosis in chemical-induced liver injury." (PMID 41009731, 2025). "In AD-induced acute lung injury, IL-22 inhibits Ang II-mediated pulmonary microvascular endothelial cell apoptosis and downregulates STAT3 expression and intranuclear delivery." (PMID 38971897, 2024). "Inhibition of FOXO1, NLRP3, HSP90, or STAT3 has been reported to promote functional recovery after brain injury." (PMID 39310540, 2024). "On the contrary, our findings are consistent with previous studies demonstrating that inhibitors of STAT3, such as Stattic, ameliorate inflammatory responses in endotoxin-induced acute lung injury." (PMID 36119052, 2022). "The experimental group had significantly higher phosphorylated signal transducer and activator of transcription 3 (p-STAT-3) protein expression levels than the positive control group in alcohol-induced acute liver injury (P < 0.05 and P < 0.01)." (PMID 35707386, 2022). "The janus kinase (JAK)–signal transducer and activator of transcription-3 (STAT3) pathway is a potent pro-survival signaling pathway during stress-induced myocardial injury, including acute MI." (PMID 34292971, 2021). "Myocardial ischemic postconditioning- (IPo-) mediated cardioprotection against myocardial ischemia-reperfusion (IR) injury needs the activation of signal transducer and activator of transcription 3 (STAT3), which involves adiponectin (APN)." (PMID 32190173, 2020). "Given the importance of STAT3 in the inflammatory response, we found that the activation of pulmonary STAT3 in CLP-induced septic lung injury mice was significantly increased compared to that in sham group." (PMID 32641132, 2020). "Our previous studies also showed that IL-32 inhibited NF-κB and STAT3 in tumor growth models as well as acetoaminophen-induced liver injury and 1-methyl-4-phenyl-1,2,3,6-tetrahydropyridine induced Parkinson models (data not shown)." (PMID 26497686, 2015). "Signal transducer and activator of transcription 3 (Stat3) plays an essential role in the pathogenesis of IgG immune complex (IC)-induced acute lung injury." (PMID 23527081, 2013). "Signal transducer and activator of transcription 3 (STAT3) is activated in response to growth factors, cytokines, and hormones that are known to play protective role after nerve injury and to mediate nerve regeneration." (PMID 22997489, 2012). "Our results show that Lachnum YM156 (LSP156) increases body mass and organ indices, reduces oxidative damage and inflammatory responses, alleviates liver tissue injury and regulates the STAT3/COX-2 signalling pathway in N-nitrosodiethylamine (NDEA)-induced liver injury mice." (PMID 41426367, 2025). "While DOXO-induced oxidative stress and NF-κB activation are well documented, our findings are the first to demonstrate that selective AURKA inhibition can simultaneously downregulate the IL-17A-driven STAT3/HIF-1α/TGF-β1/VEGF-A axis in DOXO-induced liver injury." (PMID 40872590, 2025). "The JAK2/STAT3 signaling pathway had been reported in oxidative damage of testis in mice, and it was also reported in ER stress in rat heart ischemia/reperfusion injury." (PMID 34582743, 2022). "Considering the fact that one miRNA can regulate multiple target genes, and several miRNAs can regulate the single gene to exert its effect, the modulation of MAPK14 and STAT3 during INH-induced liver injury may be conceivable." (PMID 29554950, 2018). "However, nuclear PKM2 activates STAT3 to drive hepatocyte proliferation and regeneration following injury, suggesting that targeting the PKM2–STAT3 signaling axis could be a promising therapeutic strategy in liver injury." (PMID 41148838, 2025).
injury (continued). "There are also reports that delayed exposure to ( +)Env may have a similar beneficial effect on spatial learning and enhanced memory after brain injury possibly via increased hippocampal and STAT3-HIF-1α-VEGF-mediated neurogenesis in the subventricular zone in young animals." (PMID 34382128, 2022). "For example, STAT3 activation by IL-6 potentiates proinflammatory responses in peritoneal macrophages, whereas STAT3 activation by IL-10 dampens lipopolysaccharide (LPS)-induced inflammatory responses in Kupffer cells, and STAT3 activation by IL-22 ameliorates ethanol-induced liver injury." (PMID 31931878, 2020). "STAT3 is a transcription factor that plays a key role in cytokine and growth factor signaling, it has been shown that as a transcription factor of TERT, STAT3 can up‐regulate TERT expression and plays a role in aging and repair nerve injury." (PMID 34262731, 2021). "Furthermore, corilagin attenuated the protein levels of NOX1, NOX2, signal transducer and activator of transcription 3 (STAT3), and nuclear factor kappa B (NF-κB) in APAP-induced liver injury." (PMID 36829609, 2023). "Moreover, lestaurtinib, a janus kinase and fms-like tyrosine kinase 3 (FLT3) inhibitor, was shown to attenuate acute lung injury by reducing neutrophil infiltration, which may also attenuate brain edema by inhibiting the JAK2/STAT3 pathway." (PMID 37234258, 2023). "In addition, in lipopolysaccharide (LPS)-induced acute lung injury rat model, inhibition of HSP110 could alleviate lung injury through suppressing phosphorylation of signal transducer and activator of transcription 3 (STAT3)." (PMID 35986277, 2022).
osteoporosis (45 papers, 2012 to 2026). A condition of reduced bone mass, with decreased cortical thickness and a decrease in the number and size of the trabeculae of cancellous bone (but normal chemical composition), resulting in increased fracture incidence. "Collectively, these findings support the role of asiatic acid in targeting key proteins associated with osteoporosis, particularly within the STAT3, NF-κB, and PPAR signaling pathways." (PMID 41562931, 2026). "The associations among SOCS1, AGO3, and the JAK2/STAT3 signaling pathway in osteoporosis progression were then evaluated." (PMID 41043430, 2025). "While lower BMD is shown in the femoral neck and spine in classical osteoporosis, in STAT3-HIES, only radial BMD is associated with the risk of fractures." (PMID 40040707, 2025). "Most of the skeletal abnormalities in patients with STAT3 deficiency, such as scoliosis and osteoporosis, are due to poor responses to leukemia inhibitory factor (LIF)." (PMID 40040707, 2025). "Alternatively, increased activation of STAT3 has been implicated in other bone-related disorders such as osteoporosis and osteoarthritis (OA)." (PMID 38203559, 2023). "In conclusion, our study has refined a critical role of STAT3 in exercise-mediated osteogenesis and revealed a potential therapeutic strategy for exercise loss osteoporosis." (PMID 37151888, 2023). "On the other hand, further investigation of the role of STAT3 in the development of subtypes other than oestrogen deficiency-induced osteoporosis is also important." (PMID 35879773, 2022). "In addition, STAT3-deficient mice have increased osteoclast numbers and activity resulting in osteoporosis." (PMID 40884553, 2025). "Finaly, modulation of STAT3 signaling may be targeted to treat bone metabolic diseases, such as Job’s Syndrome and menopause-associated osteoporosis." (PMID 32730332, 2020). "Therefore, bisphosphonates, which could inhibit osteoclast activity and bone resorption, was be leveraged to treat secondary osteoporosis that caused by STAT3 mutations." (PMID 34824272, 2021). "Collectively, these findings establish NF-κB p65 and PPARγ as experimentally validated hub targets of asiatic acid in osteoporosis, whereas direct modulation of IL-6 and STAT3 has remained insufficiently characterized." (PMID 41562931, 2026). "Network pharmacology identified key osteoporosis-related targets involved in inflammatory signaling, hormone regulation, and bone remodeling, with key hubs including IL-6, STAT3, NF-κB, and PPARγ." (PMID 41562931, 2026). "While this study primarily examines the PI3K/AKT signaling pathway, it is also important to investigate the role of the JAK/STAT3 signaling pathway in osteoporosis." (PMID 40332238, 2025). "To validate these findings, we examined gene expression across independent datasets and observed consistent differential expression of DDIT4, FOXO1, and STAT3 in both osteoporosis and sarcopenia cohorts, confirming their relevance as shared biomarkers." (PMID 41282482, 2025). "Results revealed significant differential expressions of DDIT4, FOXO1, NFKBIA, PGK1, and STAT3 in the osteoporosis model." (PMID 41282482, 2025). "We identified DDIT4, FOXO1, and STAT3 as three central biomarkers that play pivotal roles in the pathogenesis of both osteoporosis and sarcopenia." (PMID 41282482, 2025). "By modulating the JAK/STAT3 pathway, it is possible to inhibit bone destruction and chronic inflammation, which can lead to an improvement in osteoporosis symptoms." (PMID 40332238, 2025). "The mounting connections between STAT3 signaling and osteogenic regulation are generating increasing avenues of investigation with a goal of developing treatments for osteoporosis, as well as other diseases of bone fragility." (PMID 39689092, 2024).
osteoporosis (continued). "Osteoblast-specific STAT3 ablation resulted in decreased bone formation, craniofacial deformities, dwarfism, and osteoporosis, with heterozygous knockout mice also displaying a skeletal phenotype with osteoporosis and low mineral bone density." (PMID 38203559, 2023). "In addition, STAT3 might act as a potential target for osteoporosis caused by exercise loss." (PMID 37151888, 2023). "This review focuses on the role of STAT3 in regulating the balance of bone remodelling in osteoporosis, particularly the differentiation and function of osteoblasts and osteoclasts." (PMID 35879773, 2022). "Bazedoxifene, approved by the Food and Drug Administration (FDA) as a selective estrogen modulator for osteoporosis treatment, has been demonstrated to be a new drug that inhibits the IL-6/gp130/STAT3 pathway." (PMID 35565185, 2022). "This suggested that the related target molecules had an important role in GCK-treated osteoporosis, especially for the targets STAT3, PIK3R1, VEGFA, JAK2 and MAP2K1." (PMID 36430397, 2022). "In osteoporosis, IL-6/STAT3 signaling is closely related to the differentiation of osteoclasts and RANKL expression in osteoblasts, which are regulators of bone homeostasis." (PMID 34833909, 2021). "IL-6, IL-6/STAT3 signaling mediates various diseases, such as inflammatory bowel disease, Castleman disease, osteoarthritis, and osteoporosis." (PMID 34833909, 2021). "STAT3 also has a central role in the differentiation of osteoblasts and osteoclasts, with overactivation of STAT3 inducing osteosclerosis and suppression of STAT3 leading to osteoporosis." (PMID 24743778, 2014). "In the present study, molecular docking analysis revealed that asiatic acid exhibited stronger binding affinities toward several osteoporosis-related proteins, including STAT3, PPARγ, NF-κB p105, COX-2, ESRα, TLR4, and NF-κB p65, compared to their native ligands." (PMID 41562931, 2026). "Studies have reported that activation of signal transducer and activator of transcription 3 (STAT3) can reduce ferroptosis and promote osteoclast differentiation, which indicates that ferroptosis is important in osteoporosis by regulating osteoclast differentiation." (PMID 38650009, 2024). "It has been reported in the literature that STAT3 and its network are involved in bone remodeling and the development of osteoporosis, and some studies have found that STAT3 can play an essential role in maintaining bone development and homeostasis by regulating osteoblasts." (PMID 38650009, 2024). "Emerging evidence suggests that STAT3 and its network participate in bone remodelling and the development of osteoporosis, and this factor may be a potent target for osteoporosis treatment." (PMID 35879773, 2022). "However, recent studies have demonstrated that the activation of JAK2/STAT3 signalling is increased by some miRNAs regulation in osteoporosis samples; for example, miR-151a-3p and miR-125b." (PMID 35879773, 2022). "A number of traditional Chinese medicines inhibit osteoporosis through the JAK2/STAT3 pathway." (PMID 35879773, 2022). "Several lines of data suggested that the osteoporosis induced by STAT3 inactivation may be relevant to incremented osteoclast activity." (PMID 34824272, 2021). "However, mice in which STAT3 was conditionally deleted using TIE2 promoter driving Cre in early stages of osteoclast development exhibited osteoporosis with significantly higher osteoclast numbers." (PMID 32730332, 2020). "Drugs targeting the STAT3 pathway may be used for treatment of diseases such as Job’s Syndrome and osteoporosis." (PMID 32730332, 2020). "All of these results suggest that the relationship among CRY2, miR-7-5p, p-STAT3, and P300 likely exists in human MSCs, which may indicate a potential clinical application for a treatment strategy of osteoporosis." (PMID 31982773, 2020). "The osteoporosis observed in STAT3 LOF HIES on the other hand could be a result of the existence of a pro-inflammatory state rather than OPN deficiency." (PMID 29868029, 2018).